CTLA4 (cytotoxic T-lymphocyte associated protein 4)
Diseases named in the same sentence as CTLA4 in open-access papers (continued):
Sharing a sentence is not in itself a finding about the gene and the disease.
cancer (continued). "The advent of immune therapy against tumors, for example, the targeting of PD-1 and CTLA4 signaling pathways, have revolutionized clinical treatment of various cancers, including ccRCC." (PMID 34485161, 2021). "The CTLA-4 antibody ipilimumab works to turn off this inhibitory mechanism or “release the brakes” in order to allow T cells to target and kill cancer cells." (PMID 33796453, 2021). "Successful blockade of CTLA-4 with monoclonal antibody such as ipilimumab has shown improved outcome for cancer patients." (PMID 34531847, 2021). "This is particularly significant in cancer cells as CTLA-4 has a higher binding affinity to both ligands, compared to CD28." (PMID 34268109, 2021). "Although CTLA-4 expression is largely restricted to T cell lineages and some cancers, there are numerous indirect effects of anti-CTLA-4 therapy on innate immune subsets." (PMID 33468555, 2021). "ICTs, including anti-PD-1 and CTLA-4 therapies have completely improved therapeutic and prognostic profile for a variety of advanced cancers, including OC." (PMID 34777359, 2021). "Cancer immunotherapies by ICIs, such as antibodies against PD-L1, PD-1, and CTLA4, have achieved notable success by blocking immune-inhibitory signals and enabling patients to produce antitumor immunity." (PMID 33753855, 2021). "Although remarkable progress has been made in cancer treatment through the blockade of CTLA-4 or PD-1 signaling using monoclonal antibodies (mAbs), most patients do not respond to immunotherapy because of primary or acquired drug resistance." (PMID 34421887, 2021). "The immune checkpoint inhibitors (ICI) such as anti-CTLA-4 antibody as well as anti-PD-1, have revolutionized the treatment of several cancers but fail to control cancer progression in a significant proportion of patients." (PMID 34262562, 2021). "Here, we developed nanobody (Nb)-based ICIs to elicit CTLA4 blockade and treat canine cancer patients." (PMID 34675296, 2021). "Where, the discovery of immune checkpoint blockage or inhibition (ICB/ICI), anti-PD-1/PD-L1 and anti-CTLA4-based, therapy has revolutionized the class of cancer treatment at a different level." (PMID 34571899, 2021). "These immune checkpoint inhibitors (ICIs), including pembrolizumab, tislelizumab, nivolumab (anti PD-1) and ipilimumab (anti CTLA-4), have led to dramatic and durable clinical responses in diverse cancers." (PMID 33499003, 2021). "Immune checkpoint blockade, in particular blocking the CTLA-4 and PD-1 checkpoint pathways, represents a revolutionized form of cancer immunotherapy." (PMID 34531847, 2021). "PD-1 inhibitors (nivolumab, pembrolizumab) and anti-CTLA-4 (CD152) (ipilimumab) have revolutionized cancer therapy." (PMID 34638410, 2021). "Ipilimumab, an anti-CTLA-4 blocking monoclonal antibody, was the first immune checkpoint inhibitor to be tested and approved for the treatment of cancer." (PMID 33634137, 2021). "Currently, the use of immune checkpoint inhibitors (ICIs) such as anti-CTLA4 antibodies has markedly improved the prognosis of several cancers in their advanced stages." (PMID 34675296, 2021). "The ratios of response and clinical benefit to different ICI therapy targets (PD-1, PD-L1 and CTLA-4) across cancer subtypes were calculated and compared." (PMID 34220837, 2021). "Combination treatment targeting PD‐L1 and CTLA‐4 was utilized for cancer patients to improve the antitumor T‐cell immunity recently." (PMID 33510997, 2021). "Although not all patients benefit from these agents, ICIs are frequently used as first-line therapies in patients with other cancers exhibiting upregulated expression of PD-1, PD-L1, and/or CTLA-4." (PMID 34484197, 2021). "An increasing number of studies also incorporate CTLA-4 or PD-1 inhibitors to be used as adjuvant therapy, thereby improving anti-cancer agent activity." (PMID 34440813, 2021).
cancer (continued). "In this bidirectional way, the interplay of CD86 with CD28 and CTLA‐4 are of great importance for immune responses against autoimmunity and cancers." (PMID 33954112, 2021). "In this study, combining a simple mRNA vaccine with an anti-CTLA-4 monoclonal antibody meaningfully enhanced the anti-cancer host immune response and anti-cancer effects." (PMID 35096628, 2021). "Antibodies to block PD-1/PDL-1 and CTLA-4 immune checkpoint mechanisms are one the earliest immunotherapeutic strategies which have allowed immunotherapy to enter the mainstream of anti-cancer treatment." (PMID 33708214, 2021). "To date, seven ICIs have been approved by the FDA for various cancer types: anti-CTLA-4 mAb (ipilimumab), anti-PD-1 mAbs (pembrolizumab, nivolumab, cemiplimab) and anti-programmed cell death 1 ligand (PD-L1) mAbs (atezolizumab, durvalumab, avelumab)." (PMID 33890870, 2021). "For example, proteins expressed at the surface of T-cells (including PD-1 and CTLA-4) and their ligands (PD-L1 and B7-1/B7-2, respectively), expressed by cancer cells and antigen-presenting cells, are needed to prevent excessive immune responses." (PMID 34572736, 2021). "Studies provide evidence that the response of cancer patients to blockade of the immune checkpoints PD-1/PD-L1 or CTLA-4 is influenced by the gut microbiome." (PMID 34638420, 2021). "Recently, cancer immunotherapies, including antibodies targeting immune checkpoint molecules, such as PD-1, PD-L1 and CTLA-4, have emerged as an unprecedented breakthrough for the treatment of cancer that can induce long-term tumor regression." (PMID 33718594, 2021). "The commonly used targets of immunotherapy are mainly cytotoxic T-lymphocyte-associated protein 4 (CTLA-4) or PD-1/PD-L1, which can effectively treat a variety of malignant tumors." (PMID 34992591, 2021). "These outcomes indicate a broader regulatory role for BTLA in cancer as compared to PD-1 and CTLA-4 checkpoint axis." (PMID 34531847, 2021). "As such, checkpoint inhibitor therapies, inhibiting CTLA4 and PD-L1/PD-1, were revolutionary cancer immunotherapies (CITs) as they restored the ability of CD8+ T cells to recognize and kill cancer cells." (PMID 33564739, 2021). "Currently, the surface markers, programmed death-1 (PD-1) and CTLA-4 are well known for their function in the immune system, as well as their role in cancer as theranostic applications." (PMID 34940257, 2021). "The identified synthetic peptide can be used for the development of novel immune checkpoint inhibitors that can block CTLA-4 functional activity for cancer immunotherapy." (PMID 33419027, 2021). "Especially, agents targeted immune checkpoints such as PD-1, PD-L1 and CTLA-4 have achieved great clinical success in anti-cancer practice." (PMID 35111663, 2021). "Antibody-mediated inhibition of CTLA-4 was the first to report positive results in cancer immunotherapy." (PMID 34638281, 2021). "ICIs that target immune checkpoints like PD-1, PD-L1, or CTLA-4 and disrupt the cancer cell’s ability to evade the host immune response have become one of the key cancer therapy modalities." (PMID 34771615, 2021). "By upregulation of the CTLA-4 proteins, cancer cells exploit this co-inhibitory pathway of the immune system to further suppress immune response." (PMID 33673374, 2021). "PD-1 and CTLA-4 inhibitors exhibit promising anticancer effects in multiple cancers, including NSCLC." (PMID 33714956, 2021). "Whereas our strategy of utilizing CTLA4-targeted CAR T cells has the advantages of not only suppressing cancer cells but also blocking immune checkpoint." (PMID 33868277, 2021). "Clinically, limiting CTLA4 function by antibody blockade was proved effective as a therapeutical approach to treat various cancers by the mechanism of boosting immune response against malignant tissues." (PMID 35096593, 2021).
cancer (continued). "Immune checkpoint blockade therapies, especially anti-PD-1 and anti-CTLA4, were first approved in advanced melanoma patients and then applied for various cancers, which has dramatically impacted the cancer treatment algorithm." (PMID 34552878, 2021). "The expression of programmed death 1 (PD1)/programmed death-ligand 1 (PDL1), cytotoxic T-lymphocyte-associated antigen 4 (CTLA4), and other immune checkpoints in hypoxic malignant tumors is often significantly increased, and is associated with poor prognosis." (PMID 34012727, 2021). "Immune checkpoint inhibitors (antibodies that block the T cell co‐inhibitory receptors PD‐1/PD‐L1 or CTLA‐4) have revolutionized the treatment of some forms of cancer." (PMID 32920841, 2021). "Previous literature showed that PD-1/PD-L1 and CTLA-4 are up-regulated at the transcription level under hypoxic conditions, enhancing the immune escape of cancer cells." (PMID 34895169, 2021). "This study found that HK3 stimulates the infiltration of monocytes/macrophages presenting surface markers, regulates the key molecules PD-1 and CTLA-4 of exhaustive T cells, and affects the immune escape process of cancers." (PMID 34239350, 2021). "Several reports have demonstrated the anti-cancer activities of anti-PD-1, anti-PD-L1, and anti-CTLA-4 antibodies in those co-implantation models." (PMID 34702924, 2021). "For example, blocking antibodies against PD‐L1 or its receptor PD‐1, or the B7‐1 and B7‐2 inhibitory receptor CTLA‐4 have been used in the treatment of cancer patients." (PMID 33938620, 2021). "Inhibitory immune checkpoint blockade using anti-PD-1 and anti-CTLA4 antibodies has provided substantial benefits to certain cancer patients." (PMID 34649584, 2021). "Cancers abuse this mechanism by the secretion of tumor growth factor β (TGF-β), causing CTLA-4 expression on T cells and expression of B-7, a ligand of CTLA-4." (PMID 34884998, 2021). "In recent years, a breakthrough was made in the targeting of the three main members of the B7 family, CTLA-4, PD-1 and PD-L1 (B7-H1), in the immune checkpoint blockade treatment of cancer." (PMID 34289871, 2021). "PD-1 inhibitors, such as nivolumab, pembrolizumab and ipilimumab (anti-CTLA-4 or CD152), also block prototypical T-cell checkpoints and have revolutionized cancer therapy." (PMID 34638410, 2021). "Therapies with anti-PD-1, anti-PD-L1, or anti-CTLA-4 reinvigorate T cells as well as allow the adaptive immune system thereby targeting cancer cells." (PMID 35185859, 2021). "Immune checkpoint inhibitors (i.e. anti-PD1, anti-PDL1, and anti-CTLA4) have revolutionized the therapeutic approach of several cancer types." (PMID 34597942, 2021). "CXCL12 signaling inhibition synergizes with immune checkpoint blockade by PD-1 and CTLA-4 antibodies in mouse cancer models." (PMID 33753872, 2021). "Recent summary work on colitis suggested that most cancer patients were treated with CTLA-4 inhibitors, followed by PD-1 inhibitors, or combination therapy." (PMID 34512631, 2021). "Tregs in CML BM were activated, thymic-derived, and overexpressed receptors such as Ctla-4, Gitr, Garp, and Tgf-β1 on the surface that have been previously reported to mediate their activity and immunosuppressive function in various cancer entities." (PMID 34727093, 2021). "It is well known that immunosurveillance affects the prognosis of cancer patients and that tumors can evade immune responses and immunotherapy by taking advantage of immune checkpoint genes, such as PD-1, PD-L1, and CTLA-4." (PMID 35087869, 2021). "The most extensively used immune checkpoint inhibitors for research and application of cancer therapy include PD-1 and inhibitors of its ligand PD-L1, as well as CTLA-4." (PMID 34267742, 2021). "While various immune stimulation strategies such as checkpoint blockade of PD-1/PD-L1 or CTLA-4 have been a major step forward leading to durable responses even in patients with advanced cancers, the overall response rate is low." (PMID 33995422, 2021).
cancer (continued). "Anti-CTLA-4 antibody treatment to block CTLA-4 signaling in T cells shows promising effects in advanced cancer patients." (PMID 33483505, 2021). "Antibodies that target immune checkpoints, such as CTLA-4 or PD-1, are the current strategies for cancer immunotherapy." (PMID 34530752, 2021). "Immune checkpoint inhibitors (ICI) treatments represented by anti-PD-1/PD-L1 or anti-CTLA-4 agents have dramatically improved the survival outcome of advanced cancer patients." (PMID 34747719, 2021). "This is in sharp contrast to the impressive response to blockade of CTLA-4, PD-1, and PD-L1 seen in a broad variety of cancers of different origin, and strengthens the suggestion of the requirement for a relevant expression level of checkpoints on T cells." (PMID 34502204, 2021). "Studies revealed that CTLA4 is a new immunotherapeutic target, and inhibition of CTLA4 can promote the activation of T cells and then play an anti-cancer role." (PMID 33754011, 2021). "Immune checkpoint inhibitors (ICIs), such as programmed death-1 (PD-1), programmed death-ligand 1 (PD-L1), and cytotoxic T lymphocyte associated protein-4 (CTLA-4), have revolutionized cancer treatment." (PMID 34711664, 2021). "Thus, during cancer progression, the immune checkpoint pathways mediated by the structurally similar co-inhibitory receptors; Programmed cell Death 1 (PD-1) and the Cytotoxic T lymphocyte-associated antigen-4 (CTLA-4) or CD152 receptors are often usurped by cancer cells to evade immune surveillance." (PMID 34268109, 2021). "Recently, many studies have focused on immune checkpoint molecules, such as CTLA-4 and PD-1/PD-L1, as components of new strategies for cancer therapy, and found that these molecules can significantly regulate the immune function of TICs." (PMID 34802433, 2021). "The combination of anti-PD-1 and CTLA4 immune checkpoint inhibitors in several cancers demonstrated better efficacy than monotherapy." (PMID 35127473, 2021). "Therapeutic monoclonal antibodies (mAbs) targeting the immune checkpoints cytotoxic T lymphocyte-associated protein 4 (CTLA-4) and programmed cell death 1 (PD-1) have revolutionized the treatment of various cancers." (PMID 33196890, 2021). "In the 1990s, Allison and colleagues identified the therapeutic potential of CTLA4 inhibition, which culminated in the development and use of ICIs targeting CTLA4 for cancer therapy." (PMID 35154081, 2021). "Tremelimumab is another anti-CTLA-4 inhibitor that is currently under investigation in clinical trials for various cancers, e.g., melanoma, malignant pleural mesothelioma, SCLC, and NSCLC." (PMID 34201650, 2021). "Evidence for that has been seen in the regulation of immune checkpoint proteins such as CTLA4 in MDSCs by intracellular PUFA levels in cancer models." (PMID 35095900, 2021). "So far, the Food and Drug Administration has approved 7 antagonistic monoclonal antibodies (mAbs) against cytotoxic T-lymphocyte-associated protein-4 (CTLA-4), programmed cell-death protein-1 (PD-1), and its ligand PD-L1 for treatment of cancer." (PMID 33712537, 2021). "By targeting the immune checkpoint in TME, anti-cytotoxic T-lymphocyte associated protein 4 (CTLA4), anti-programmed cell death 1 (PD-1), and anti-CD274/PD-L1havebeen shown to be the most effective immunotherapy methods for cancer." (PMID 34827528, 2021). "Further, the most common side effect of anti-CTLA-4 immunotherapy in cancer patients is enterocolitis, most likely due to increased intestinal levels of the pro-inflammatory cytokines IFNγ and IL-17A." (PMID 33802979, 2021). "The subgroup analysis of PFS was only based on the cancer histological type, because 19 of the trials used PD-1 inhibitors, while only one trial used a combination of PD-1 and CTLA-4 inhibitors." (PMID 34086601, 2021). "The inclusion of monoclonal antibodies targeting immune checkpoints such PD-1/PD-L1 or CTLA-4 has revolutionized the landscape of anti-cancer therapy." (PMID 33925565, 2021).
cancer (continued). "Cancer cells exploit checkpoint activation through these PD-1 and CTLA-4 pathways to induce anergy in antitumor T cells." (PMID 34680601, 2021). "Apart from the regulatory subset of T cells, we also studied other T cell subpopulations, such as PD-1 and CTLA-4 T cells, mainly involved in different pathways as immune checkpoint in cancer." (PMID 34572849, 2021). "In the last few years, targeting co-inhibitory receptors with monoclonal antibodies has shown impressive results in tumor regression and overall survival, leading to the approval of anti-CTLA-4, anti-PD-1, and anti-PD-L1 in numerous cancers." (PMID 34208480, 2021). "While various immune stimulation strategies such as PD-1/PD-L1 or CTLA-4 checkpoint blockade result in robust responses, even in patients with advanced cancers, the overall response rate is low." (PMID 33995422, 2021). "Cytotoxic T-cells play a pivotal role in anticancer immunity, and T-cell infiltration determines a favorable prognosis for many cancers as well as sensitivity to inhibitors of immune checkpoint receptors, including PD-L1, PD-1, and CTLA-4." (PMID 34950592, 2021). "Recent studies have demonstrated increased levels of soluble counterparts of CTLA-4, B7-1, and B7-2 in the plasma of cancer patients." (PMID 34531847, 2021). "mAbs targeting ICPs such as CTLA-4 and PD-1/PD-L1 have changed the field of immune-oncology because of their potent effects in a diversity of human cancers." (PMID 33712537, 2021). "Immune-checkpoint inhibitors targeting cytotoxic T-lymphocyte antigen 4 (CTLA-4), programmed cell death-1 (PD-1), and programmed cell death-1-ligand 1 (PD-L1) have provided substantial benefits to many cancer patients." (PMID 34680601, 2021). "Recently, cancer immunotherapy has been attracting much attention because of the successful clinical application of immune checkpoint inhibitors targeting the CTLA-4 and PD-1/PD-L1 pathways." (PMID 34065346, 2021). "The recent success of immune checkpoint blockade, using anti‐PD‐1, PD‐L1, or CTLA‐4 antibodies, has demonstrated the power of the immune system in fighting cancer." (PMID 33752265, 2021). "Cancer immunotherapy with anti-CTLA-4 antibodies modulates the balance of the microbiota–intestinal barrier by inducing IEC-mediated intestinal epithelial cell (IEL) apoptosis, resulting in disruption of the barrier." (PMID 33401586, 2021). "Immune checkpoint inhibitors (ICIs), such as programmed cell death 1 (PD-1), programmed death-ligand 1 (PD-L1), and cytotoxic T-lymphocyte antigen 4 (CTLA-4), have been developed as effective agents in cancer immunotherapy." (PMID 34065315, 2021). "Monoclonal antibodies, such as anti-PD-1/PD-L1 or anti-CTLA-4, are successfully used in cancer immunotherapy." (PMID 34203292, 2021). "The efficacy of anti-PD-L1 plus anti-CTLA-4 highlights the potential benefit of combined immunotherapy and we provide a source for the selection of cancer-dependent or even individualized combinations." (PMID 34135436, 2021). "Recently, immune checkpoint therapy targeting the PDL1/PD1 axis and CTLA-4 has been reported to be a promising strategy for immunotherapy of cancer." (PMID 34938753, 2021). "Checkpoint inhibitors, such as anti-PD-L1 and anti-CTLA4 antibodies, are widely used as adjuncts to radiation for restoring T-cell activation and enabling T cells to control cancer progression." (PMID 33469123, 2021). "The phenomenon is more frequent during anti-CTLA-4 therapy and tends to affect fewer cancer patients treated with anti-PD-1/L1 agents." (PMID 34768681, 2021). "CTLA-4 is the first checkpoint receptor that has been successfully studied and tested in cancer as a target." (PMID 34440249, 2021). "Modulators of the immune checkpoints, in particular antibodies inhibiting CTLA4 (Ipilimumab), PD-1 (Cempilimab, Nivolumab or Pembrolizumab) or PD-L1 (Durvalumab, Avelumab or Atezolizumab) have heralded a new dawn for cancer therapy." (PMID 35006469, 2021).